PDE8A (phosphodiesterase 8A)
Diseases named in the same sentence as PDE8A in open-access papers (continued):
Sharing a sentence is not in itself a finding about the gene and the disease.
tumor (24 papers, 2019 to 2025). "For example, exosomal circ-PDE8A has been showed association with tumor progression and lymphatic invasion in pancreatic ductal adenocarcinoma (PDAC) via the miR338/MACC1/MET pathway." (PMID 35505392, 2022). "Of note is the exosomal communication between tumor cells that identifies the tumor-released exosomes in the circulation and that high levels of circPRMT5 and circ-PDE8A in plasma exosomes of tumor patients are associated with tumor progression and prognosis." (PMID 33912560, 2021). "Currently, exosomal circ-PDE8A was reported to be associated with tumor progression and lymphatic invasion by the miR-338/MACC1/MET pathway in pancreatic ductal adenocarcinoma." (PMID 31277663, 2019). "It is suggested that exosomal circ-PDE8A could be a valuable diagnostic for PDAC diagnosis or prognosis, and circ-PDE8A plays a crucial role in tumor invasion." (PMID 38590433, 2024). "detected the exosomal circRNA expression profile of PDAC cells with liver metastasis by microarray technology and found that high circ-PDE8A expression was associated with lymphoid infiltration, tumor-node-metastasis (TNM) stage, and poor survival in PDAC patients." (PMID 35505392, 2022). "They found that exosomal circ-PDE8A was associated with progression and prognosis in PDAC patients playing a pivotal role in tumor invasion." (PMID 37189687, 2023). "In pancreatic cancer, the tumor-released exosomal circRNA PDE8A promotes aggressive growth through the miR-338/MACC1/MET pathway." (PMID 35505392, 2022). "Exosomal circ‐PDE8A derived from plasma of PDAC patients has been reported to promote tumor invasion by upregulating MET (MET proto‐oncogene, receptor tyrosine kinase)." (PMID 34766148, 2021). "Circ-PDE8A, a highly contained and stable circular RNA screened out from tumor exosomes, is overexpressed in PDAC tissues and is an independent risk factor for PDAC survival." (PMID 32083078, 2020). "Further research shows that circ-PDE8A promotes tumor cell growth by upregulation of MET, a tyrosine kinase receptor that is one of the key oncogenes in a subset of epithelial tumors including PDAC." (PMID 33324638, 2020). "Considering specific examples, tumour exosomes containing an increased volume of circ-PDE8A and circ-IRAS were identified in the systemic circulation of PDAC patients." (PMID 33158116, 2020). "In further, researchers have proven that the level of circ-PDE8A is extremely high in the serum exosomes of PDAC patients, which indicates that exo-circ-PDE8A enhances tumor invasion through exosome-mediated communication." (PMID 30925885, 2019). "Furthermore, circ-PDE8A facilitated tumor cell growth by increasing the expression of MET (a tyrosine kinase receptor), encoded by one of the vital oncogenes for a subclass of epithelial tumors, containing PDA." (PMID 34987636, 2022). "Exosomal circ-PDE8A stimulates tumor invasion by miR-338/MACC1/MET/AKT or ERK pathways." (PMID 36338993, 2022). "In addition, circ-PDE8A excreted by the tumor can be released into the blood circulation through exosome transport, acting as ceRNA of miR-338, regulating MACC1 and promoting invasive metastasis through MACC/MET/ERK or AKT pathways." (PMID 33324638, 2020). "Further, they found that circ-PDE8A excreted by tumor could be released into blood circulation through exosome transportation." (PMID 32083078, 2020). "Moreover, tumor-excreted circ-PDE8A could be released into blood circulation by exosome transportation, acting as a ceRNA for miR-338 to regulate MACC1 and promote invasive metastasis through the MACC/MET/ERK or AKT pathways." (PMID 31277663, 2019). "Therefore, circ-PDE8A may play a pivotal role in tumor invasion." (PMID 35505392, 2022). "Here, we summarize ncRNAs with tumor-promoting functions: HOTAIR, HOTTIP, MALAT1, lncRNA H19, lncRNA PVT1, circ-RNA ciRS-7, circ-0030235, circ-RNA_100782, circ-LDLRAD3, circ-0007534, circRHOT1, circZMYM2, circ-IARS, circ-RNA PDE8A, miR-21, miR-155, miR-221/222, miR-196b, miR-10a." (PMID 32257946, 2020).
cancer (7 papers, 2014 to 2024). A tumor composed of atypical neoplastic, often pleomorphic cells that invade other tissues. "In this study, it was uncovered that circ-PDE8A inhibits the function of miRNA-338, consequently escalating the levels of metastasis-associated in colon cancer 1 (MACC1), a target of miRNA-338." (PMID 32756339, 2020). "Since MACC1 is a positive regulator of c-MET, a receptor for hepatocyte growth factor, circ-PDE8A activates downstream signaling factors, such as Akt and ERK1/2, thereby promoting invasive growth and metastasis of cancer cells." (PMID 32756339, 2020). "After the initial observation that PDE8A is expressed in T cells, several reports documented the role of PDE8 in controlling T cell and cancer cell motility." (PMID 27601994, 2016).
infection (2 papers, 2011 to 2014). The state of being infected such as from the introduction of a foreign agent such as serum, vaccine, antigenic substance or organism. "The effect of PDE8A on Pol proviral DNA levels was already mediated within the first 24-hours post infection, whereas levels of strong stop proviral DNA as determined by R/U5 qPCR were not affected." (PMID 25295610, 2014). "Knockdown of PDE8A expression resulted in a decrease in Pol proviral DNA levels at 48-hours post-infection." (PMID 25295610, 2014). "HEK293T cells overexpressing PDE8A showed a dose dependent increase in Pol proviral DNA at 48-hours post infection." (PMID 25295610, 2014). "Next, we analyzed the effect of PDE8A overexpression on early steps of the viral replication cycle by analysis of proviral DNA levels during 48-hours post infection." (PMID 25295610, 2014). "Subsequent infection with a VSV-G/NL-4-3.Luc reporter virus, resulted in a significant decrease in luciferase activity in the PDE8A knockdown cells, demonstrating that HIV-1 replication in macrophages is supported by PDE8A." (PMID 25295610, 2014).
PDE8A also shares sentences with these, for which no sentence is quoted: colon cancer (2 papers); acute kidney injury (1); asthma (1); chronic hepatitis C virus infection (1); gastric tumor (1); glucose metabolism disorder (1); hyperlipidemia (1); Infertility (1); liver cancer (1); Obesity (1); ovarian carcinoma (1).